C9orf57 (chromosome 9 open reading frame 57)
Tractability: Antibody: UniProt predicts a signal peptide or a membrane-spanning region.
Gene: Protein-coding gene on chromosome 9 (72,051,376 to 72,072,721, reverse strand). Ensembl gene ENSG00000204669.
Subcellular location: Membrane
Gene Ontology:
Cellular component: membrane
Genetic constraint (gnomAD): Loss-of-function variants: 10 observed, 10.56 expected, observed/expected ratio (o/e) 0.95, 90% interval 0.58 to 1.59. The upper end of that interval is the gene's LOEUF score, 1.59, which puts it in group 6 of 6, group 1 being the genes least tolerant of losing a copy. Missense variants: 139 observed, 161.56 expected, observed/expected ratio (o/e) 0.86, 90% interval 0.75 to 0.99. Synonymous variants: 49 observed, 57.76 expected, observed/expected ratio (o/e) 0.85, 90% interval 0.67 to 1.08.
Homologues: Orthologues: chimpanzee C9H9orf57 (98% identical).